OXA1L (OXA1L mitochondrial inner membrane insertase)
Description:
Mitochondrial membrane insertase that mediates the cotranslational insertion of integral membrane proteins into the mitochondrial inner membrane. Essential for the activity and assembly of cytochrome oxidase. Required for the correct biogenesis of ATP synthase and complex I in mitochondria.
Synonyms: MGC133129; OXA1; OXA1L1
Tractability: Small molecule: a structure with a bound ligand is known. Antibody: UniProt predicts a signal peptide or a membrane-spanning region. PROTAC: ubiquitination databases record sites on it; its protein half-life has been measured.
Gene: Protein-coding gene on chromosome 14 (22,766,522 to 22,773,042, forward strand). Ensembl gene ENSG00000155463.
Subcellular location: Mitochondrion inner membrane
Subcellular location (Human Protein Atlas): Mitochondria
Pathways (Reactome):
Metabolism of proteins: Mitochondrial ribosome-associated quality control; Mitochondrial translation elongation; Mitochondrial translation initiation; Mitochondrial translation termination
Metabolism: Complex I biogenesis
Gene Ontology:
Molecular function: membrane insertase activity; mitochondrial ribosome binding; protein binding; protein homodimerization activity
Biological process: aerobic respiration; mitochondrial protein quality control; mitochondrial proton-transporting ATP synthase complex assembly; mitochondrial respiratory chain complex I assembly; negative regulation of ATP-dependent activity; negative regulation of oxidoreductase activity; protein insertion into mitochondrial inner membrane from matrix; protein tetramerization; mitochondrial translation
Cellular component: mitochondrial inner membrane; mitochondrial membrane; mitochondrion; protein-containing complex; mitochondrial matrix; membrane
Genetic constraint (gnomAD): Loss-of-function variants: 38 observed, 48.73 expected, observed/expected ratio (o/e) 0.78, 90% interval 0.6 to 1.02. The upper end of that interval is the gene's LOEUF score, 1.02, which puts it in group 4 of 6, group 1 being the genes least tolerant of losing a copy. Missense variants: 532 observed, 541.97 expected, observed/expected ratio (o/e) 0.98, 90% interval 0.91 to 1.05. Synonymous variants: 225 observed, 202.09 expected, observed/expected ratio (o/e) 1.11, 90% interval 1 to 1.24.
Gene-disease validity (ClinGen):
ClinGen rates the evidence that OXA1L causes each of these diseases.
mitochondrial disease (autosomal recessive): Limited.
Homologues: Orthologues: chimpanzee OXA1L (99% identical), macaque OXA1L (92% identical), rabbit OXA1L (81% identical), pig OXA1L (80% identical), dog OXA1L (80% identical), guinea pig OXA1L (78% identical), mouse Oxa1l (74% identical), rat Oxa1l (74% identical), tropical clawed frog oxa1l (49% identical), zebrafish oxa1l (48% identical), Drosophila melanogaster OXA1L (34% identical), Caenorhabditis elegans oxa-1 (22% identical). Paralogues in human: COX18 (18% identical).
Diseases named in the same sentence as OXA1L in open-access papers:
OXA1L is named in the same sentence as 23 diseases in open-access papers, as found by Europe PMC text mining. Sharing a sentence is not in itself a finding about the gene and the disease. The quoted sentences say what the papers report.
Mitochondrial encephalopathy (4 papers, 2018 to 2025). "OXA1L is crucial for mitochondrial protein insertion and assembly into the inner mitochondrial membrane, and its variants have been recently linked to mitochondrial encephalopathy." (PMID 40551575, 2025). "Here, we present the clinical, biochemical and molecular characterisation of a patient with a severe, childhood‐onset mitochondrial encephalopathy and combined respiratory chain deficiency due to biallelic variants in OXA1L identified by WES." (PMID 30201738, 2018).
developmental delay (3 papers, 2013 to 2022). "Here, we describe a case of mitochondrial disease caused by mutations in OXA1L, which leads to a severe encephalopathy, hypotonia and developmental delay." (PMID 30201738, 2018). "We used whole exome sequencing to identify recessively inherited variants in OXA1L (NM_005015.3; c.500_507dup, p.(Ser170Glnfs*18) and c.620G>T, p.(Cys207Phe) in a patient with a mitochondrial disorder, presenting at birth with hypotonia, severe encephalopathy and developmental delay." (PMID 30201738, 2018).
asthma (2 papers, 2015 to 2023). "The variants or polymorphisms in the OXA1L gene were associated with asthma and allergy by regulating the biogenesis and mitochondrial oxidative phosphorylation." (PMID 37114785, 2023). "In addition, eQTL analysis suggests that rs1999071 at 14q21, associated with asthma in this study, regulates the expression of OXA1L in lung tissue." (PMID 26635092, 2015).
mitochondrial encephalomyopathy (1 paper, 2025). A heterogenous group of disorders characterized by alterations of mitochondrial metabolism that result in muscle and nervous system dysfunction. "GSEA revealed down‐regulated changes in skeletal muscle organ development genes and up‐regulated changes in mitochondrial encephalomyopathy associated genes in OXA1L KO IHSMC." (PMID 40551575, 2025). "Though OXA1L has traditionally been included in diagnostic panels for combined MRC defects, there is presently only one publication linking OXA1L gene variant to mitochondrial encephalomyopathy." (PMID 40551575, 2025).
Mitochondrial myopathy (1 paper, 2025). "Together, our findings reinforce the genotype–phenotype association between OXA1L variations and mitochondrial diseases and further delineate the potential molecular mechanisms of how OXA1L deficiency causes skeletal muscle deficits in mitochondrial myopathy." (PMID 40551575, 2025). "In this study, we report the second mitochondrial myopathy case carrying bi‐allelic variants in OXA1L gene, one of which is a novel variant." (PMID 40551575, 2025). "We employed hiPSC‐derived myotube differentiation model to shed light on the morphofunctional pathways underlying mitochondrial myopathy resulting from OXA1L bi‐allelic variants." (PMID 40551575, 2025). "Our work not only adds to our current knowledge on mitochondrial myopathy associated with bi‐allelic pathogenic variants in OXA1L, but also provides a potential target for the intervention of mitochondrial diseases." (PMID 40551575, 2025). "In summary, we identified bi‐allelic OXA1L variants in a Chinese girl with mitochondrial myopathy, which broadens the mutation spectrum and reinforces the genotype–phenotype association between OXA1L variations and mitochondrial diseases." (PMID 40551575, 2025). "In this study, we reported the second family with mitochondrial myopathy harbouring bi‐allelic variants in the OXA1L gene, broadening mutation spectrum and providing new evidence for the association between OXA1L variants and mitochondrial diseases." (PMID 40551575, 2025). "Given the functional diversity of OXPHOS, further research is warranted to clarify other undiscovered molecules or signalling pathways that may be implicated in the initiation and progression of OXA1L‐related mitochondrial myopathy." (PMID 40551575, 2025). "Above findings suggested that the bi‐allelic variants c.620G>T and c.1163_1164del in OXA1L gene may be pathogenic genetic factors responsible for the mitochondrial myopathy in this individual." (PMID 40551575, 2025). "In this study, we identified bi‐allelic variants of c.620G>T, p.(Cys207Phe) and c.1163_1164del, p.(Val388Alafs*15) in OXA1L gene in a mitochondrial myopathy patient using whole exome sequencing." (PMID 40551575, 2025). "Moreover, skeletal muscle conditional Oxa1l knockout mice exhibited OXPHOS deficiencies and skeletal muscle morphofunctional abnormalities, recapitulating the phenotypes of mitochondrial myopathy." (PMID 40551575, 2025). "Based on our findings, we speculate that NF‐κB signalling pathway activation mediated by elevated ROS from OXA1L deficiency‐induced OXPHOS impairment may influence myogenic programming and apoptosis, which may be a potential pathogenic mechanism leading to mitochondrial myopathy." (PMID 40551575, 2025).
osteoporosis (1 paper, 2021). A condition of reduced bone mass, with decreased cortical thickness and a decrease in the number and size of the trabeculae of cancellous bone (but normal chemical composition), resulting in increased fracture incidence. "Compared with the control group, HIST1H3G, NOP2, OXA1L, and ZFPM2 were upregulated in osteoporosis, and MAP3K5 was downregulated." (PMID 33778083, 2021).
Right ventricular cardiomyopathy (1 paper, 2016). Right ventricular dysfunction (global or regional) with functional and morphological right ventricular abnormalities, with or without left ventricular disease. "Also of interest is the plakophilin 2 gene (PKP2), associated with right ventricular cardiomyopathy and multiple genes involved in mitochondrial energy metabolism (MTCH1, OXA1L, MUL1)." (PMID 27923400, 2016).
Skeletal myopathy (1 paper, 2025). "The mechanistic link between OXA1L deficiency‐induced mitochondrial abnormalities and skeletal myopathy remains incompletely understood." (PMID 40551575, 2025).
mitochondrial disease (4 papers, 2018 to 2025). "Although in silico and functional evidence suggest these variants disrupt OXA1L function, further validation in expanded patient cohorts is essential to establish a causal link between OXA1L variants and mitochondrial disease." (PMID 40551575, 2025). "Despite the fact that our findings enhance the association between OXA1L variants and mitochondrial diseases, the limited number of reported cases currently precludes definitive genotype–phenotype correlations." (PMID 40551575, 2025). "Given the genotype–phenotype heterogeneity of mitochondrial disease, and the fact that only two cases with OXA1L bi‐allelic variants have been reported, determining why our patient has a different phenotype from the first family is tough." (PMID 40551575, 2025). "There has been only a single report in the literature regarding OXA1L mutations underlying a mitochondrial disease presentation." (PMID 38612624, 2024). "The association between OXA1L gene variation and mitochondrial disease as well as the underlying pathophysiological mechanisms remains unclear, necessitating further exploration through additional clinical cases and functional experiments." (PMID 40551575, 2025). "However, the definitive pathogenic link between OXA1L variants and mitochondrial diseases as well as the underlying pathogenesis remains elusive." (PMID 40551575, 2025). "Our study documents the first case of mitochondrial disease caused by mutations in OXA1L." (PMID 30201738, 2018). "By contrast, OMIM lists no established phenotype for the OXA1L gene, however, biallelic OXA1L gene variants have been associated with mitochondrial disease." (PMID 41282472, 2025). "There have not been any previous reports of OXA1L mutations in mitochondrial disease patients." (PMID 30201738, 2018).
cancer (2 papers, 2019 to 2020). A tumor composed of atypical neoplastic, often pleomorphic cells that invade other tissues. "We finally obtained eight bona fide cancer driver genes, including CEP57, HNRNPL, KLF5, OXA1L, PAFAH1B1, RBM39, SYT13, and TFDP1." (PMID 31925297, 2020). "In addition, we noticed seven of them have been included in the latest version of The Network of Cancer Genes35 (KLF5, OXA1L, RBM39, and TFDP1) or CancerMine36 (HNRNPL, KLF5, PAFAH1B1, SYT13, TFDP1), two manually curated cancer gene databases, further confirming our findings." (PMID 31925297, 2020).
tumor (1 paper, 2021). "OXA1L showed inconsistent trends in the tumor and metastatic samples." (PMID 34124242, 2021).
OXA1L also shares sentences with these, for which no sentence is quoted: bacteremia (2 papers); Encephalopathy (2); Allergy (1); Epstein-Barr virus infection (1); healthcare-associated infections (1); hereditary spastic paraplegia (1); lactic acidosis (1); nematode infection (1); Sepsis (1); tuberculosis (1); urinary tract infection (1); virus infection (1).